IFNG (interferon gamma)
Diseases named in the same sentence as IFNG in open-access papers (continued):
Sharing a sentence is not in itself a finding about the gene and the disease.
pancreatic cancer (continued). "In another study with 79 Stage III/IV pancreatic cancer patients, IRE treatment along with allogeneic natural killer cell therapy was tested and demonstrated that IRE alone and IRE with NK cell therapy increases IFNγ expression." (PMID 35372046, 2022). "Moreover, NM reverses immune resistance induced by interferon-gamma (IFN-ɤ) as a method of increasing programmed cell death ligand-1 (PD-L1) expression in lung and pancreatic cancer." (PMID 31552177, 2019). "IFNγ could be used to down-regulate the expression of FOXM1 through STAT1 phosphorylation, thereby increasing the sensitivity of pancreatic cancer cells to gemcitabine." (PMID 30782607, 2019). "However, to the best of our knowledge, specific IFNγ production to EBV and CMV in patients with pancreatic cancer or brain tumor remains unexplored." (PMID 29970101, 2018). "Specifically CTL, NKT, γδT, NK, and IFNγ (Th1 type) cells were up-regulated, and Th17, PMN-MDSC, IL-6 and IL-8 (Th2 type) immune cells were inhibited, suggesting embelin can inhibit pancreatic cancer growth and inflammation by modulating tumor immune microenvironment." (PMID 24694877, 2014). "Specifically, patients with GBM presented the lowest IFNγ increase production to CMV-pp65 and EBNA-1 (ΔIFNγ production median respectively only + 200 and + 291.2 pg/ml) that were significantly lower that the patients with pancreatic cancer (p < 0.001, ΔIFNγ production median up to + 2800 pg/ml)." (PMID 29970101, 2018). "Lastly, although the authors observed inverse correlations between EPHA2 and CTL gene signatures in human pancreatic cancer, we did not discover any consistent trends between EPHA2 and CD3E, CD8B, GZMA, GZMB, PRF1, or IFNG expression from the TCGA lung adenocarcinoma dataset." (PMID 40867322, 2025).
periodontitis (160 papers, 2009 to 2026). An acute or chronic inflammatory process that affects the tissues that surround and support the teeth. "The objective of this study was to evaluate the association and role of IFNg polymorphisms, such as IFNg +874 A/T, and the susceptibility to periodontitis." (PMID 34784626, 2022). "Out of the panel of 22 SNPs in 13 cytokine genes, we identified the A allele of SNP rs240561 in IFNγ as a risk indicator for severe periodontitis in RA patients." (PMID 30890897, 2019). "In contrast, the more common C allele is associated with greater hBD1 and hBD3 expression in IFNγ-stimulated keratinocytes and is likely to be protective in conditions with elevated IFNγ such as chronic periodontitis." (PMID 19712472, 2009). "TNFα was significantly elevated in t1DM patients with gingivitis (p < 0.0001) and periodontitis (p = 0.02), while IFNγ showed a significant increase only in healthy diabetic individuals (p = 0.02)." (PMID 41280935, 2025). "Mechanistically, periodontitis fostered ectopic colonization of P. zoogleoformans in the lungs, upregulating the infiltration of IFNγ+ T cells and ultimately intensifying the severity of PH." (PMID 38548721, 2024). "We evaluated the effects of ω-3 PUFA on the cytokines TNFα, IL-2, IFNγ, IL-4, and IL-5 in a P. gingivalis ligature-induced periodontitis in the serum of mice." (PMID 37378834, 2024). "This study aims to investigate the IFNg +874A/T polymorphic genotypes in Indonesian subjects, comparing patients with severe and mild periodontitis and the level of IFNg." (PMID 34784626, 2022). "In the intercellular network, BTLA and IFNG signals are strongly activated in the circulatory system during periodontitis." (PMID 36329504, 2022). "Compared to SH, CD4 + T cells were significantly activated by periodontitis microbiota, with the accumulation of IFNγ+ CD4 (p < 0.05), IL17+ CD4 (p < 0.05), and IL22+ CD4 (p < 0.05) T cells in the small intestine." (PMID 35756043, 2022). "A recent animal study in mice showed that periodontitis affects course of Th1 profile cells and related cytokines (especially interferon gamma), leading to pulmonary alterations." (PMID 35676670, 2022). "Although the role of IFNG in osteoclast differentiation and activity has been extensively studied, little is known about its role in periodontitis and peri-implants." (PMID 35581339, 2022). "IL-1, tumor necrosis factor alpha (TNF-α), and interferon gamma (IFN-γ) are important cytokines which are highly involved in the progression of periodontitis." (PMID 34566966, 2021). "The group showed that periodontal therapy was correlated with alterations of PTGS2 gene methylation in patients with CP, while DNA methylation levels of TNF and IFNG remained unchanged in the periodontitis group after periodontal therapy." (PMID 32867386, 2020). "Thereby an increase of pro-inflammatory cytokines such as interleukin (IL)-1β, -2, -6, -8, tumour-necrosis-factor (TNF), and interferon-gamma (IFN-γ) was seen in periodontitis, while a decrease of inflammation was detected after periodontal treatment." (PMID 33153049, 2020). "In this model, IFNG mRNA expression was even higher than in periodontitis patients, but returned to the levels seen in periodontal health after resolution of inflammation." (PMID 33256844, 2020). "Clinical studies investigating the impact of the IFNγ level on periodontitis showed an increased expression in saliva and gingival biopsies in chronic periodontitis as well as in gingival crevicular fluid in periodontal active sites." (PMID 30890897, 2019). "Peripheral blood mononuclear cells (PBMCs) from patients with chronic periodontitis have been shown to produce large amounts of inflammatory cytokines including IFNγ and TNFα and differentiate to osteoclasts with high resorption activity by RANKL alone." (PMID 30158833, 2018). "This includes periodontitis which has been considered a Th1 type condition with elevated levels of IFNγ in gingival fluid of active periodontal lesions." (PMID 19712472, 2009).
periodontitis (continued). "Mutual exacerbation of periodontitis and COPD is associated with the activation of γδ T cells and M2 macrophages, ultimately leading to increased expression of IL‐17 and interferon gamma (IFN‐γ), as well as M2 macrophage polarization." (PMID 39811802, 2025). "Periodontitis is originated by the presence of dysbiotic dental biofilm, with subsequent stimulation of the host response and release of pro-inflammatory molecules as interferon-gamma (IFN-γ), interleukins, tumour necrosis factor." (PMID 40356307, 2025). "Starting with a report that the methylation of CpG sites in the promoter of IFNγ was significantly higher in the gingiva of periodontitis patients, methylation of TLR2 promoter, TNF-α promoter, and others were reported to be associated with periodontitis." (PMID 36294882, 2022). "Consistent with the results in our study, periodontitis microbiota could activate Th1, Th17, and Th22 lymphocytes by increasing the cytokines level of IFNγ, IL17, and IL22 in the small intestine." (PMID 35756043, 2022). "SLE patients had a worse periodontitis due to high IFNγ levels." (PMID 33861790, 2021). "Interestingly, the production of interferon gamma is one central aspect concerning the NK cell-mediated mechanism in periodontitis, as increased levels of interferon gamma are predictive for the severity of periodontal disease." (PMID 33371393, 2020). "Chronic periodontitis vs. healthy patients against experimentally induced gingivitis Zhang’s group (2010) determined DNA methylation levels within the IFNG promotor in gingival biopsy samples from subjects with CP compared to experimentally induced gingivitis and healthy controls." (PMID 32867386, 2020). "In addition, LPS is related to interferons in innate immune response, and there is a correlation between interferon-gamma in the crevicular fluid and periodontitis." (PMID 30875931, 2019). "In particular, tumor necrosis factor-α (TNFα) and interferon-gamma (IFNγ) are believed to promote bone degradation in periodontal disease, because periodontal tissues in patients with periodontitis are infiltrated by CD4+ and CD8+ T cells, which produce these cytokines." (PMID 30158833, 2018). "Besides osteoclastogenesis, increased apoptosis of osteoblasts induced by IFNγ and TNFα has been demonstrated in mouse models of periodontitis." (PMID 30158833, 2018). "Mechanistically, periodontitis dysregulated the pulmonary microbiota by promoting ectopic colonization and enrichment of oral bacteria in the lungs, contributing to pulmonary infiltration of interferon gamma positive (IFNγ+) T cells and aggravating the progression of pulmonary hypertension." (PMID 38548721, 2024). "In addition, we identified Prevotella zoogleoformans as the critical periodontitis-associated bacterium driving the exacerbation of pulmonary hypertension by periodontitis, and the exacerbation was potently ameliorated by both cervical lymph node excision and IFNγ neutralizing antibodies." (PMID 38548721, 2024). "In another study, gingival samples from patients with chronic periodontitis showed higher levels of pro-inflammatory cytokines, such as IL-2, TNF-α, interferon gamma (IFN-γ), and IL-17A, when compared to healthy gingival tissues." (PMID 39916927, 2023). "IL6, IL6R, IFNG, PTGS2, SOCS1, and TNF were identified as candidate genes that have been assessed for DNA methylation in periodontitis." (PMID 32867386, 2020). "Similar heterogeneity of DNA methylation within individual promoters and site-specific differences between healthy donors and patients with periodontitis have been observed for the TNF and IFNG genes analyzed by pyrosequencing." (PMID 33256844, 2020). "In our study, however, the IFNγ/IL4 imbalance was also observed in response to TT, an Ag irrelevant to periodontitis." (PMID 23335969, 2013).
periodontitis (continued). "The inflammatory microenvironment in periodontitis is characterized by elevated levels of cytokines, including interleukin-1β (IL-1β), tumor necrosis factor-alpha (TNF-α), and interferon-gamma (IFN-γ), which contribute to the breakdown of the extracellular matrix and alveolar bone loss." (PMID 40136681, 2025). "The subjects with severe periodontitis showed marginally but not significantly higher levels of IFNg compared with subjects with mild periodontitis (p > 0.05)." (PMID 34784626, 2022). "This suggests that NK cell-secreted IFNG stimulates mDCs to induce and maintain an inflammatory response in patients with periodontitis but can be ameliorated by non-surgical therapy." (PMID 36329504, 2022). "Similarly, the CCL pathway, which is known to augment the production of IFNG from the CCL5‒CCR1 interaction, was strongly upregulated in periodontitis patients, which supports the higher activity of INFG." (PMID 36329504, 2022). "In periodontitis, aberrant genes highlighted include interleukin-1, interleukin-6, interleukin-10, transforming growth factor-beta (TGF-β), tumor necrosis factor-α (TNF-α), interferon-gamma (IFN-γ), and matrix metalloproteinases (MMPs) among others." (PMID 33869630, 2021). "Curiously, this increase in gene expression in individuals with experimental gingivitis was not accompanied by decreased IFNG promoter methylation, which was noted in patients with periodontitis assessed in parallel." (PMID 33256844, 2020). "In addition, smokers had higher IFNγ mRNA and protein levels in gingival tissues compared to non-smokers with comparable types of periodontitis." (PMID 34572311, 2021). "The current study revealed that the levels of Th1 cytokines IFNG and IL12 did not change between healthy and periodontitis-affected gingival samples while that of TNF slightly increased in periodontitis." (PMID 27531006, 2016). "It is important to note the discrepancies between the reports: in the case of IFNG, IL6, IL8, TNF, and TLR2, the differences in promoter methylation between patients with periodontitis and healthy individuals observed in some studies have not been reproduced in independent analyses." (PMID 33256844, 2020).
gastric cancer (153 papers, 2011 to 2026). A primary or metastatic malignant neoplasm involving the stomach. "Our study revealed a decrease in IFNγ in patients with gastric cancer at stages I, II, and III of the disease compared with the control group and the group of patients at stage IV (p1–2 < 0.001, p1–3 < 0.001, p1–4 < 0.001, p2–4 = 0.02)." (PMID 40806737, 2025). "In gastric cancer liver metastases, NK cells showed reduced expression of IFNγ and TNF, partially driven by TGFβ-mediated suppression." (PMID 40621458, 2025). "A crucial finding of the pathway analysis was the inhibition of three immune-related pathways in the CDKN2A ALT gastric cancer patients, including the interferon alpha response, inflammatory response, and interferon gamma response." (PMID 38822443, 2024). "MTMR2 promotes invasion and metastasis of gastric cancer via inactivating IFNγ/STAT1 signaling and modulates TIME by promoting the progression of NK/T cell lymphoma by targeting JAK1." (PMID 39408697, 2024). "Another strategy is to use the median value of IFNγ as cut-off as was done by Cho and colleagues in a gastric cancer cohort, and by Lee and colleagues in a pancreatic ductal adenocarcinoma cohort." (PMID 37137997, 2023). "Death-associated protein kinase 1 (DAPK1) is a positive mediator of interferon-gamma-induced programmed cell death and is a tumour suppressor candidate that inhibits tumour immune evasion in gastric cancer." (PMID 37065474, 2023). "IFNγ increases integrin β3 expression via upregulating p50/p65 phosphorylation and induces gastric cancer cell proliferation and metastasis." (PMID 33406733, 2021). "In gastric cancer, head and neck cancers, and cholangiocytes, IFNγ induces PD-L1 expression through the JAK/STAT1 pathway." (PMID 34445462, 2021). "On the other hand, IFNγ treatment induced cell cycle arrest in the G1/S phases and suppressed cell proliferation in gastric cancer." (PMID 33406733, 2021). "The extent of T-cell migration toward culture supernatants obtained from interferon-gamma (IFN-γ-stimulated gastric carcinoma cell lines was additionally affected by expression of PML in vitro." (PMID 22022583, 2011). "Interestingly, we found that the expression of GSDMB increased when gastric cancer cells were treated with IFNγ, consistent with Shao and co‐workers findings." (PMID 37587833, 2023). "IFNγ may additionally enhance gastric cancer immunosuppression by inducing hepatocyte growth factor receptor (HGFR/MET)-mediated PD-L1 expression." (PMID 33406733, 2021). "When gastric cell lines were treated with the HDAC inhibitor vorinostat after IFNγ induction, B7-H1 was reduced, showing that HDACs play a role in the IFNγ enhancement of B7-H1 in gastric cancer and are involved in the evasion phenotype of these malignant cells." (PMID 34439300, 2021). "In Keynote-012 clinical trial, the average levels of six interferon-gamma-related genes (CXCL9, CXCL10, IDO1, IFNG, HLA-DRA, and STAT1) were associated with OS (p=0.0047) and PFS (p=0.0009) in patients with head and neck squamous cell carcinoma and gastric cancer treated with pembrolizumab." (PMID 34367136, 2021). "Moreover, increased galectin-3 expression in gastric cancer cells contributes to cellular unresponsiveness to interferon gamma (IFN-γ) by facilitating the AKT/GSK-3β/SHP2 signaling cascade." (PMID 29389859, 2018). "Thus, in the case of EBV+ gastric carcinomas, EBNA1 may induce both constitutive and IFNγ-inducible PD-L1 expression in EBV (+) gastric carcinoma cells." (PMID 29719817, 2018). "The expression of IFNG, a marker of effector function, is increased in MSI-H gastric cancer than in MSS gastric cancer." (PMID 40626015, 2025). "In another study, human gastric cancer patient tumour MDSCs suppressed T cells ex vivo via IL-10, resulting in a decrease in CD4+ T cell production of IL-2 and IFNγ consistent with impaired effector function." (PMID 38464388, 2024).
gastric cancer (continued). "Moreover, analysis of the TCGA gastric cancer database (n = 375) showed that expression of IFNG was positively correlated with IDO1 expression in GC." (PMID 38994917, 2024). "Of particular note, we observe increased enrichment of interferon gamma signaling terms with age in most ICB-approved cancers, including colon, esophageal, head and neck, kidney, lung, and gastric cancer cohorts." (PMID 34433020, 2021). "Studies have demonstrated that gastric cancer with EBV (+) and microsatellite instability (MSI) can elicit interferon gamma (IFN-γ) driver genes, which induce the expression of PD-L1/2 through the signal transducer and activator of transcription (STAT) family." (PMID 34178648, 2021). "Tumor-infiltrating lymphocyte (TIL)-driven IFNγ stimulates the JAK2/STAT1 pathway, leading to increased PD-L1 expression in gastric cancer." (PMID 33406733, 2021). "In patients with gastric cancer at stage IV of the disease, multidirectional changes occur when studying proinflammatory cytokines: a decrease in TNF-α, IL-8, TNF-β, as well as an increase in IL-2, IFNγ, IL-17A, and IL-6." (PMID 40806737, 2025). "In patients with gastric cancer at stages I, II, and III of the disease, there is an increase in such proinflammatory cytokines as TNF-α, IL-2, IL-8, TNF-β, IL-17A, and IL-6, as well as a decrease in IFNγ." (PMID 40806737, 2025). "In our study, we observed that TFF1 expression was downregulated in gastric cancer-derived KATO III cells upon exposure to IFNγ alone, whereas in primary human gastric mucosoids, its repression required a combination of TNF-α, IL-1β, and IFNγ." (PMID 41573568, 2025). "We demonstrate that CC-3 induces profound T cell reactivity against various pancreatic, hepatic and gastric cancer cell lines as revealed by analysis of activation, degranulation and secretion of IL2, IFNγ as well as perforin, resulting in potent target cell lysis." (PMID 37122707, 2023). "For example, cisplatin and IFNγ have been shown to upregulate PDL1 on cell lines of HNSCC and the secretion of this cytokine by activated CTL at the tumor site play a key role in the upregulation this checkpoint molecules in gastric cancer cells." (PMID 31214178, 2019). "Knockdown of METTL14 and YTHDF1 could reduce mRNA transcript levels of interferon signaling IFNA/IFNB/IFNG/ISG5, which is involved in the formation of the gastric cancer (GC) microenvironment and suppresses the antitumor immunity mediated by interferon signaling blocking." (PMID 36226062, 2022). "Similar to our results, a gastric cancer study found that neither G-CSF, GM-CSF, TGF-β, M-CSF, IL-1β, IL17A, IL-6, TNFα, IL10, IFNγ and IL22 were able to induce MC degranulation, while only adrenomedullin did." (PMID 32722549, 2020).